KDELR2 (KDEL endoplasmic reticulum protein retention receptor 2)
Description:
Membrane receptor that binds the K-D-E-L sequence motif in the C-terminal part of endoplasmic reticulum resident proteins and maintains their localization in that compartment by participating to their vesicle-mediated recycling back from the Golgi. Binding is pH dependent, and is optimal at pH 5-5.4 (By similarity).
Synonyms: ELP-1; ERD2.2; OI21
Tractability: Antibody: UniProt predicts a signal peptide or a membrane-spanning region. PROTAC: ubiquitination databases record sites on it.
Gene: Protein-coding gene on chromosome 7 (6,445,953 to 6,484,193, reverse strand). Ensembl gene ENSG00000136240.
Subcellular location: Endoplasmic reticulum membrane; Golgi apparatus membrane; Cytoplasmic vesicle, COPI-coated vesicle membrane
Pathways (Reactome):
Vesicle-mediated transport: COPI-dependent Golgi-to-ER retrograde traffic; COPI-mediated anterograde transport
Gene Ontology:
Molecular function: ER retention sequence binding
Biological process: maintenance of protein localization in endoplasmic reticulum; retrograde vesicle-mediated transport, Golgi to endoplasmic reticulum; protein retention in ER lumen
Cellular component: COPI-coated vesicle membrane; endoplasmic reticulum membrane; Golgi membrane; membrane; transport vesicle; endoplasmic reticulum
Genetic constraint (gnomAD): Loss-of-function variants: 9 observed, 11.92 expected, observed/expected ratio (o/e) 0.76, 90% interval 0.45 to 1.32. The synonymous counts are far from expectation, so gnomAD's model fits this gene poorly and the ratio says little. Missense variants: 161 observed, 126.89 expected, observed/expected ratio (o/e) 1.27, 90% interval 1.12 to 1.45. Synonymous variants: 79 observed, 57.89 expected, observed/expected ratio (o/e) 1.36, 90% interval 1.14 to 1.64.
Homologues: Orthologues: mouse Kdelr2 (99% identical), pig KDELR2 (99% identical), chimpanzee KDELR2 (97% identical), macaque KDELR2 (96% identical), rat Kdelr2 (95% identical), rabbit KDELR2 (95% identical), dog KDELR2 (94% identical), guinea pig KDELR2 (94% identical), zebrafish kdelr2b (93% identical), zebrafish kdelr2a (92% identical), tropical clawed frog kdelr1 (89% identical), Drosophila melanogaster KdelR (74% identical), and 2 more. Paralogues in human: KDELR1 (83% identical), KDELR3 (75% identical).
Diseases named in the same sentence as KDELR2 in open-access papers:
KDELR2 is named in the same sentence as 34 diseases in open-access papers, as found by Europe PMC text mining. Sharing a sentence is not in itself a finding about the gene and the disease. The quoted sentences say what the papers report.
glioblastoma (9 papers, 2020 to 2025). The most malignant astrocytic tumor (WHO grade IV). "Recent studies have shown that KDELR2 is highly expressed in glioblastoma, mediating the phosphorylation level of mTOR, thereby promoting glioblastoma proliferation." (PMID 39513664, 2024). "For example, several published researches suggested that KDELR2 can be a promotive factor for the tumorigenesis of glioblastoma and breast cancer." (PMID 37791813, 2023). "The KDELR2 is highly expressed in glioblastoma (GBM) tissues and negatively correlated with patients’ survival." (PMID 35399533, 2022). "KDELR2 is a poor prognostic factor for glioblastoma and acts as a direct target of HIF-1α, a regulator of p-mTOR as well as the downstream protein in glioblastoma cells." (PMID 36096734, 2022). "Recent studies have revealed that upregulated KDELR2 expression level in glioblastoma tissues promotes the tumorigenesis and shortens the lifetime, making the receptor an interesting rapeutic target in glioblastoma patients." (PMID 32645101, 2020). "KDELR2 expression was enhanced in various tumour tissues, including breast cancer, head and neck cancer, kidney cancer, liver cancer, lung cancer, colon cancer, bladder cancer and glioblastoma." (PMID 37791813, 2023). "Interestingly, the KDEL receptor (KDELR2) can also target and promote the growth of HIF1a through the mTOR signaling pathway to guide glioblastoma." (PMID 36474171, 2022).
osteogenesis imperfecta (7 papers, 2021 to 2024). Osteogenesis imperfecta (OI) comprises a heterogeneous group of genetic disorders characterized by increased bone fragility, low bone mass, and susceptibility to bone fractures with variable severity. "The importance of KDELR2 is supported by the finding that its mutation causes osteogenesis imperfecta and neurodevelopmental delay." (PMID 39115595, 2024). "Bi-allelic variants of the KDELR2 gene have recently been described in patients with osteogenesis imperfecta (OI), a rare heterogeneous connective tissue disorder characterized by susceptibility to bone fractures along with neurodevelopmental disorders." (PMID 35740256, 2022). "In addition, known mutations in KDELR1 and KDELR2 are associated with lymphopenia and osteogenesis imperfecta, respectively, making KDEL receptor replacement an attractive therapeutic strategy for these conditions." (PMID 34063979, 2021). "KDELR2-related osteogenesis imperfecta results from the inability of the collagen-chaperone, heat shock protein 47 (HSP47), to bind KDELR2; this prevents the dissociation of HSP47 from type 1 collagen." (PMID 35740256, 2022).
glioma (5 papers, 2020 to 2025). A benign or malignant brain and spinal cord tumor that arises from glial cells (astrocytes, oligodendrocytes, ependymal cells). "KDELR2 knockdown enhances glioma cell apoptosis through multiple mechanisms, including activation of the CHOP and JNK/p38 pathways." (PMID 40767982, 2025). "Of these, ten genes (CTSZ, EFEMP2, ITGA5, KDELR2, MDK, MICALL2, MAP 2 K3, PLAUR, SERPINE1 and SOCS3) can potentially classify patients with gliomas into different risk groups." (PMID 32878880, 2020). "KDELR2 knockdown could inhibit the viability of glioma cells, promote cell cycle arrest at the G1 phase and induce apoptotic cell death by targeting CCND1." (PMID 36096734, 2022). "The existing research state that human glioma tissues and cell lines highly express KDELR2." (PMID 36096734, 2022). "KDELR2 is a novel biomarker that is highly expressed in high-grade gliomas." (PMID 36035134, 2022). "Furthermore, KDELR2 can regulate cellular function in glioma cells by targeting CCND1." (PMID 36474171, 2022). "Multiple studies have shown that KDELR2 is highly expressed in GBM tissues and that its expression levels are negatively correlated with glioma patient prognosis, suggesting its potential as a prognostic marker." (PMID 40767982, 2025).
bladder cancer (4 papers, 2023 to 2025). "According to research findings, KDELR2 had been found to contribute to the advancement of bladder cancer and was often associated with unfavorable outcomes in individuals who had been diagnosed with cancer." (PMID 39691708, 2024). "In an effort to delve deeper into the impact of KDELR2 on the patient outcome in cases of bladder cancer, we conducted in vitro experiments." (PMID 39691708, 2024). "KDELR2 was instrumental in promoting macrophage infiltration into the TME of bladder cancer, where it influenced the polarization of macrophages towards the M2 phenotype." (PMID 39691708, 2024). "KDELR2 was also shown to enhance bladder cancer cell proliferation, invasion, and migration, highlighting it as a promising target for macrophage-focused drug development." (PMID 39691708, 2024). "In future research, we plan to start with KDELR2 and further investigate macrophage-targeted therapeutic strategies for bladder cancer." (PMID 39691708, 2024). "By exploring KDELR2’s mechanisms in bladder cancer, we aim to develop novel therapeutic strategies to improve patient prognosis." (PMID 39691708, 2024). "KDELR2 accelerates the development of breast cancer, non-small cell lung cancer, bladder cancer, and GBM." (PMID 37114037, 2023). "For instance, HSPA5 has been recently shown to serve as a prognostic marker that promotes the proliferation and metastatic spread of the disease by regulating ferroptosis in bladder cancer, whereas KDELR2 enhances Golgi-mediated secretion to promote bladder cancer growth and metastasis." (PMID 40026699, 2025). "Thus, targeting KDELR2 presented a promising therapeutic strategy to disrupt these pro-tumorigenic processes and improve treatment outcomes in bladder cancer." (PMID 39691708, 2024). "Accordingly, we could achieve the purpose of improving prognostic survival by inhibiting KDELR2, making it possible focus for therapeutic intervention in cases of bladder cancer." (PMID 39691708, 2024). "Future studies could have explored combining KDELR2 targeting with these existing therapies to improve the efficacy of macrophage-based immunotherapies in bladder cancer." (PMID 39691708, 2024). "Therefore, the potential of targeting KDELR2 should be acknowledged as a viable strategy in the management of patients diagnosed with bladder cancer." (PMID 39691708, 2024). "Hence, KDELR2 was considered a promising therapeutic target, and the development of drugs aimed at KDELR2 could provide new treatment options for bladder cancer patients." (PMID 39691708, 2024). "Though KDELR2’s role in bladder cancer had not yet been fully explored, its involvement in other cancers suggested it could also be crucial in bladder cancer development." (PMID 39691708, 2024).
breast carcinoma (3 papers, 2023 to 2025). "In breast cancer, HDAC3 is upregulated in tumour tissues, and KDELR2 has been identified as a target of this deacetylase." (PMID 40767982, 2025).
lung carcinoma (3 papers, 2022 to 2023). "Invasion and metastasis of cells are dependent on KDELR2-regulated Golgi secretion, and KDELR2 suppression lessens lung cancer metastasis, according to a new study." (PMID 37114037, 2023). "KDELR2 has been reported to be a robust and independent driver of lung cancer invasion and metastasis." (PMID 36096734, 2022). "Overexpression of KDELR2 is sufficient to independently trigger lung cancer invasion and metastasis by an EMT-independent mechanism." (PMID 36096734, 2022).
non-small cell lung carcinoma (3 papers, 2022 to 2024). A group of at least three distinct histological types of lung cancer, including non-small cell squamous cell carcinoma, adenocarcinoma, and large cell carcinoma. "KDELR2, a key driver of non-small cell lung cancer invasion and metastasis, can be effectively targeted by inhibiting matrix metalloproteases to suppress invasion, presenting a potential treatment strategy for non-small cell lung cancer." (PMID 39104534, 2024). "Indeed, KDELR2 overexpression promotes the metastatic phenotype in non-small cell lung cancer (NSCLC) by increasing MMP1, MMP2 and MMP9 secretion and thus cell invasive ability." (PMID 35399533, 2022).
melanoma (2 papers, 2020 to 2025). A malignant, usually aggressive tumor composed of atypical, neoplastic melanocytes. "NRAS Q61L melanomas were most enriched for modules 7 (C19orf10, ARF4, KDELR2), 13 (TIMM50, ZBED3-AS1, SERPINF1), and 15 (RAP1GAP, OCA2, PAICS)." (PMID 39796775, 2025). "Virtually all melanoma cell lines in the NCI60 were characterized by elevated KDELR3 expression, but reduced or unchanged expression of KDELR1 and KDELR2, respectively." (PMID 31949145, 2020).
ovarian carcinoma (1 paper, 2013). A malignant neoplasm originating from the surface ovarian epithelium. "Although each alteration is infrequent, ROS1 fusions with many kinds of 5′ partner genes (CCDC6, CD74, EZR, KDELR2, LRIG3, SDC4, SLC34A2 and TPM3) have been reported in lung, brain, biliary tract, and ovarian cancers." (PMID 23418494, 2013).
thyroid carcinoma (1 paper, 2023). "On the other hand, KDELR2 expression was reduced in thyroid carcinoma." (PMID 37791813, 2023).
tumor (10 papers, 2021 to 2025). "Significant association was found between increased KDELR2 expression and poor characteristic for clinical stage, N stage, tumour histological type, histological grade, smoking status, and OS events." (PMID 37791813, 2023). "Firstly, we divided tumor cell lines of different sources into three groups: si-NC, si-KDELR2-1 and si-KDELR2-2." (PMID 39691708, 2024). "By modulating cytokine and chemokine production, KDELR2 helped recruit macrophages that secreted factors supporting tumor growth." (PMID 39691708, 2024). "In summary, KDELR2 had obvious tumor promoting effect, which played a key role in the development of TCs." (PMID 39691708, 2024). "Overall, the effect of PTPN12, IDH2, P2RX4, and KDELR2 on tumor immune cell infiltration is a complex process that typically involves multiple molecular pathways and signaling pathways." (PMID 37563735, 2023). "The results were adjusted based on tumour purity, and a significant correlation between KDELR2 expression and markers for Treg, monocyte, and TAM sets were identified." (PMID 37791813, 2023). "In non-small cell lung cancer, KDELR2 can enhance the secretion of matrix metalloproteases and thus promote tumor invasion and metastasis." (PMID 37791813, 2023). "Functionally, the overexpression of KDELR2 and KIF20A markedly promoted proliferation, migration, and invasion in vitro and enhanced tumor growth in vivo, while knockdown of KDELR2 and KIF20A exerted the opposite effects." (PMID 36096734, 2022). "As evidenced by IHC staining, the expression levels of KIF20A, MMP-2, MMP-9 and MKI67 increased significantly in tumor tissues in the KDELR2 overexpression group." (PMID 36096734, 2022). "Supporting the results obtained in vitro, the xenograft experiments showed that the tumor volume and weight significantly increased in the KDELR2 overexpression group." (PMID 36096734, 2022). "We also observed a significant reduction in tumor volume and weight in the stable KDELR2 silence group." (PMID 36096734, 2022). "Furthermore, in vitro studies with GBM cell lines showed that KDELR2 down-regulation inhibits cell proliferation and tumour growth while significantly increasing apoptosis." (PMID 40767982, 2025). "KDELR2 could enhance tumor immune infiltration, inhibit anti-tumor immune response, and lead to low response to immunotherapy in patients." (PMID 39691708, 2024). "Through a series of studies, we discovered that KDELR2 promoted tumor cell development." (PMID 39691708, 2024). "Increasing evidence has revealed that cellular KDELR2 has more complex roles in tumor progression." (PMID 36096734, 2022). "Furthermore, T24 cells were injected into the footpads of nude mice to construct a lymph node metastasis model to confirm the role of KDELR2 in facilitating tumor metastasis." (PMID 36096734, 2022). "Additionally, overexpression of KIF20A resulted in an increased tumor growth, which also reversed KDELR2 silence-induced decreased tumor growth." (PMID 36096734, 2022). "In addition, we investigated the effect of KDELR2 on tumor cell activity." (PMID 39691708, 2024). "Thus, the tumor-promotive function of KDELR2 on MMP2 and MMP9 might be tissue/cell-specific." (PMID 36096734, 2022). "Additionally, in subcutaneous xenograft mouse models, KDELR2 knockdown in GBM cells leads to slower tumour proliferation, resulting in significantly reduced tumour weight and volume." (PMID 40767982, 2025). "It has been found that KDELR2 stimulates ECM degradation by inducing Src activation at the invadopodia and leads to phosphorylation of the Src substrates, cortactin, thereby promoting tumor metastasis and invasive growth." (PMID 34093830, 2021). "Besides this, the KDELR2 overexpression in GBM cells significantly increases mTOR phosphorylation, suggesting that KDELR2 could activate the mTORC1 pathway, which is correlated with cell proliferation and tumor aggressiveness." (PMID 35399533, 2022).
cancer (5 papers, 2021 to 2024). A tumor composed of atypical neoplastic, often pleomorphic cells that invade other tissues. "Extracellular matrix degradation is an important process in the growth and invasion of malignant tumors, and previous research revealed that KDELR2 can potently enhance extracellular matrix degradation through activation of KDELR-Src pathway and enhancement of Golgi-mediated secretion of MMPs." (PMID 37791813, 2023). "KDELR2 expression was upregulated in various cancers, including BLCA." (PMID 37791813, 2023). "Thirdly, the possibility that the DEGs identified in the present study are directly related with cancer progression rather than KDELR2 can not be denied." (PMID 37791813, 2023). "Therefore, our findings elucidate a hitherto unexplored mechanism of KDELR2 and KIF20A in BCa, linking a Golgi‐ER traffic transport protein to a critical kinesin during cancer progression." (PMID 36096734, 2022). "C1S, FAM20C, KDELR2, and RCAN2 have rarely been reported in cancer." (PMID 33579282, 2021).
infection (1 paper, 2019). The state of being infected such as from the introduction of a foreign agent such as serum, vaccine, antigenic substance or organism. "Microscopically, the signals for KDELR2 and MV-H were clearly separated and did not reveal any co-localization at all time points after infection, but rather excluded each other." (PMID 30621148, 2019).
KDELR2 also shares sentences with these, for which no sentence is quoted: bladder urothelial carcinoma (2 papers); colon cancer (2); skin cutaneous melanoma (2); adrenocortical carcinoma (1); Baraitser-Winter syndrome 1 (1); cerebellar ataxia (1); chronic obstructive pulmonary disease (1); diffuse large B-cell lymphoma (1); head and neck cancer (1); hypogonadotropic hypogonadism (1); kidney cancer (1); leukodystrophy (1); liver cancer (1); lymphoid neoplasm (1); lymphopenia (1); Mental retardation, autosomal dominant 48 (1); osteosarcoma (1); rectum adenocarcinoma (1); sarcoma (1); thymoma (1); uveal melanoma (1).